CD1A (CD1a molecule)
Diseases named in the same sentence as CD1A in open-access papers (continued):
Sharing a sentence is not in itself a finding about the gene and the disease.
leukemia (11 papers, 2013 to 2025). A malignant (clonal) hematologic disorder, involving hematopoietic stem cells and characterized by the presence of primitive or atypical myeloid or lymphoid cells in the bone marrow and the blood. "This immunophenotype was further established as CD1− cells from high-risk T-ALL showed drug resistance and patients with CD1a− T-ALL had a decreased leukemia-free survival compared to the CD1a+ subtype." (PMID 40805157, 2025). "The CD7+CD1a− subset from primary patient samples exclusively responded to proliferation signals and efficiently initiated leukemia in a xenograft mouse model." (PMID 40805157, 2025). "On the basis of this CD1a restricted pattern of expression and selective T-ALL target, a recent in vitro and in vivo study with anti-CD1a CAR-T cells showed promising anti-leukemia effects." (PMID 35740552, 2022). "For example, the combination of GM-CSF, IL-4, and TNFα induced the expression of MHC II, CD40, CD86, CD1a, CD1b, and CD1c by neutrophil-committed precursors isolated from leukemia patients receiving G-CSF treatments." (PMID 24278484, 2013). "Within this dataset, genes such as CBFB, SEPTIN9, CBFA2T3, CD1A, and ERG have been previously reported to be closely associated with leukemia development and progression. qPCR analysis further confirmed the reduced expression levels of these genes in IRF2BP2‐knockdown cells." (PMID 39454110, 2024). "Using T-leukemia NSG mouse model, we found that CD1a CAR-T cells effectively destroyed YAP1-KO T leukemic cells, but not the control leukemic cells, leading to the prolonged survival of the mice; however, this killing process was abrogated by Lat-A treatment." (PMID 38360940, 2024). "Other positive markers were CD2/5/7 associated with CD8 expression without CD1a, therefore consistent with ALL pre-T/T (ALL-European Group of Immunological Markers for Leukemias scoring of TII/TIII)." (PMID 35334633, 2022). "There are four subtypes of T-ALL according to the European Group for the Immunological Classification of Leukemia (EGIL): pro-T EGIL T-I (iCD3+, CD7+), pre-T EGIL T-II (iCD3+, CD7+ and CD5/CD2+), cortical T EGIL T-III (iCD3+, Cd1a+, sCD3+/−), and mature-T EGIL T-IV (iCD3+, sCD3+, CD1a−)." (PMID 33810515, 2021). "In 22/24 recipients injected with hCD45+ G+C+ cells (FACS sorted from day 24–25 N+ LTB-transduced CB cultures), we obtained G+C+ leukemias of T-cell lineage, typically CD7+ CD2+ sCD3+/− CD1a+/− and variable CD4/CD8 pattern including CD4− CD8− (DN), CD4+ CD8+ (DP), and CD4− CD8dim (SP8dim)." (PMID 31266935, 2019). "The immunohistochemical study revealed that 90% of the CD20+ lymphoid cells were CD25+; Cyclin D1+ cells were positive in a small percentage of the leukemia cells; CD1a, TdT, and CD10 were not expressed by the bone marrow cells; and CD34+ cells were present in 1–2% of the blasts." (PMID 40126222, 2025). "Only CD7+CD1a− leukemia cells successfully engrafted in NS122 recipients, while CD7− and CD7+CD1a+ cells showed no engraftment." (PMID 40805157, 2025).
Rosai-Dorfman disease (10 papers, 2016 to 2026). "It is noteworthy that liver biopsies from patients with LCH-associated SC may not reveal CD1a+ cells but instead show CD1a-negative inflammatory infiltration, which may confuse the diagnosis with Rosai Dorfman disease." (PMID 39575110, 2024). "The histiocytosis, when present, most closely resembles Rosai-Dorfman disease (RDD), which is characterized by infiltrating CD68+, S100+, and CD1a− histiocytes." (PMID 33284430, 2021). "The diagnostic criteria for Rosai-Dorfman disease are large histiocytic cells that stain positive for CD68 and S100, but negative for CD1a." (PMID 42016174, 2026). "Rosai-Dorfman disease was originally described as sinus histiocytosis with massive lymphadenopathy.This rare benign disorder is characterized by the proliferation of non-Langerhans histiocytes that exhibit emperipolesis, S100+, CD68+, CD30+, CD1a- and Langerin-." (PMID 38575975, 2024). "An immunohistochemical analysis demonstrated that the histiocyte-like cells were positive for S100 and CD68PGM1 and negative for CD1a and CD207, confirming the diagnosis of cutaneous Rosai-Dorfman disease (CRDD)." (PMID 42094958, 2026). "In this case, the cells were negative for both CD1a and S-100 proteins, ruling out LCH, Rosai-Dorfman disease, and indeterminate dendritic cell tumor." (PMID 40226148, 2025). "Rosai-Dorfman disease histiocytes are typically positive for CD68, CD163, and S100, while negative for CD1a and langerin." (PMID 40398847, 2025).
atopic dermatitis (9 papers, 2017 to 2025). "Other studies showed that high affinity IgE receptor FceRI was upregulated in CD1a+ Langerhans cells in patients with atopic dermatitis and in DCs in the nose and bronchi of allergic patients." (PMID 28696399, 2017). "In humans, CD56bright CD16− NK cells are present in the dermis of healthy skin and were also found in skin from patients with atopic eczema/dermatitis, where they were in close contact with CD1a+ dendritic cells." (PMID 28063176, 2017). "In atopic dermatitis, CD1a+CD11b+CD1c+ myeloid DCs and plasmacytoid DCs were observed in the skin." (PMID 28696399, 2017). "One argument in favor of this hypothesis is given by the analysis of skin lesions of atopic dermatitis patients where NK cells were detected in the epidermis in close contact with CD1a+ dendritic cells, while all CCL18-expressing cells in the epidermis were CD1a+." (PMID 33918621, 2021). "CCR5 may also play an important role in atopic dermatitis, and expression of CCR5 on langerin-negative CD1a+ DCs was characteristic for acute AD." (PMID 38476235, 2024).
lymphoma (9 papers, 2013 to 2025). A malignant (clonal) proliferation of B- lymphocytes or T- lymphocytes which involves the lymph nodes, bone marrow and/or extranodal sites. "The only other previously reported occurrences of CD1a expression by T-cells is in some hematological malignancies such as precursor T-cell lymphoblastic leukemias and lymphomas." (PMID 25343480, 2014). "Rarely, T-lymphoblastic leukemia/lymphoma with an entirely mature immunophenotype, lacking expression of TdT, CD34, CD1a, and CD99, has been reported in children, and has been associated with poor prognosis, as have cases of T-lymphoblastic leukemia/lymphoma that are TdT negative." (PMID 40227608, 2025). "The immunohistochemistry in this case presented positive S100, CD1a, and CD68 markers and negative CD30, discarding other diseases as lymphoma, which was sufficient to confirm the diagnosis." (PMID 39958088, 2025). "In HSTCL, the lymphoma cells are typically double negative (CD4−CD8−) even if a subset of cases are CD8+, positive for CD3, CD2, CD7, and negative for CD1a and CD5." (PMID 38790955, 2024). "In particular, the lack of CD1a expression excluded LCH, while the absence of clonality, along with the mixed inflammatory background and absence of atypical lymphoid populations, did not support a diagnosis of lymphoma." (PMID 40895985, 2025).
dermatitis (8 papers, 2017 to 2024). An inflammatory process affecting the skin. "We observed that CD1a-antibody-dependent depletion of LCs was associated with reduced skin inflammation upon administration of antibodies OX110 and OX116, which may be of therapeutic importance to the treatment of inflammatory conditions." (PMID 36477177, 2022). "Experiments with human CD1a-transgenic mice show that urushiol triggers CD1a-dependent skin inflammation driven by Th17 cells (secretion of IL-17) and Th22 cells (secretion of IL-22)." (PMID 37629154, 2023). "Imiquimod-induced skin inflammation resulted in increased T-cell number and activation in CD1a-Tg blood and spleen, in addition to the skin and draining LN, compared to WT." (PMID 36477177, 2022). "Strikingly, antibody OX116 reduced the level of CD1a-Tg ear skin inflammation significantly below that of WT skin." (PMID 36477177, 2022). "The results reported here and previously published by our laboratory and others lead us to propose that CD1a contributes to the initiation and amplification of local and systemic events during skin inflammation." (PMID 36477177, 2022). "Here we propose a previously unappreciated mechanism by which skin inflammation can affect systemic immunity through CD1a-dependent effects, defining the pathway as a potentially broad therapeutic target." (PMID 36477177, 2022). "To evaluate the role of CD1a in an alternative model of skin inflammation, we employed the MC903 experimental dermatitis model." (PMID 36477177, 2022). "Nevertheless, a recent study using CD1a transgenic mice reported that the expression of this molecule is responsible for the pathogenesis of poison-induced dermatitis and psoriasis." (PMID 33081391, 2020). "This mouse showed that CD1a expression markedly exacerbated skin inflammation in response to imiquimod-induced dermatitis, which mimics certain downstream events in psoriasis." (PMID 29152228, 2017). "Through the generation of a CD1a transgenic mouse and autoreactive human CD1a-restricted T-cell lines, and the characterization of anti-CD1a antibodies, the data presented here demonstrate that CD1a amplifies the cutaneous and systemic response in murine models of skin inflammation." (PMID 36477177, 2022). "Here authors show that transgenic expression of human CD1a in mice leads to the escalation of experimental skin inflammation and systemic inflammatory disease, and the generalized symptoms could be alleviated by blocking antibodies developed against CD1a." (PMID 36477177, 2022). "We next sought to determine whether our observation of CD1a-dependent systemic inflammation in the imiquimod model of murine skin inflammation would extend to alternative pathways of inflammation." (PMID 36477177, 2022). "Dermatitis was located in the superficial dermis without the involvement of the epidermis, with CD1a+ cells mainly located around the blood vessels, and CD8+ T cells were only occasionally observed in the epidermis." (PMID 35938810, 2022). "CD1a-Tg mice showed no aberrant skin inflammation at steady state; however, we did observe a baseline increase in immune populations within the skin, including T cells and LCs." (PMID 36477177, 2022). "This work also showed that treatment with CD1a-blocking antibodies mitigated skin inflammation without comorbidity or side effects, supporting CD1a as a safe target for coT-ALL treatment." (PMID 33081391, 2020).
Granuloma (8 papers, 2007 to 2021). A compact, organized collection of mature mononuclear phagocytes, which may be but is not necessarily accompanied by accessory features such as necrosis. "Pulmonary Langerhans cell histiocytosis (PLCH) is a rare disorder characterised by granulomatous proliferation of CD1a-positive histiocytes forming granulomas within lung parenchyma, in strong association with tobacco smoking, and which may result in chronic respiratory failure." (PMID 25433492, 2014). "Our results demonstrate that BCL2A1 staining improved delineation of LCH granulomas compared to CD1a staining." (PMID 35127485, 2021). "We therefore sought firstly to confirm the finding of Badalian-Very using another methodology i.e. analyzing flow sorted CD1a+ cells from fresh LCH granuloma tissue instead of paraffin embedded biopsies." (PMID 22506009, 2012). "In this study, LCs, as defined by their positivity for CD1a, were found in varying concentrations within the epidermis, papillary dermis and granulomas in all samples tested." (PMID 17927586, 2007). "We then aimed to compare relative mutation abundance of V600E B-RAF mutations between CD1a+ and CD1a− cells from LCH granuloma, and whether mutations can be detected in the peripheral blood of patients." (PMID 22506009, 2012). "Histologic examination of a pre-therapy lymph node biopsy specimen revealed non-caseating granulomas with sheets of CD1A−/CD207−/fascin+/CD163+/factorXIII−/PGM1+ histiocytes." (PMID 28512266, 2017). "Hence, LCH granulomas were better highlighted through BCL2A1 staining rather than CD1a expression in both mononucleated cells and in MGCs (asterisk)." (PMID 35127485, 2021). "Interestingly, proliferating cells in LCH granulomas are mostly endothelial cells, fibroblasts, and T cells, as CD1a+ LCH-DCs do not proliferate, albeit they display an extended lifespan due to the activation of survival pathways and inhibition of apoptosis." (PMID 35127485, 2021).
leprosy (7 papers, 2007 to 2025). Leprosy is a chronic infectious disease affecting primarily the skin and peripheral nervous system. "Langerhans cells in leprosy skin lesions express CD1a, which is associated with reactional episodes in leprosy." (PMID 38739634, 2024). "CD1a+ cells are associated with the outcome of reactional episodes in leprosy." (PMID 29643852, 2018). "CD1a+ cells are implicated in the local immunological events taking place after mycobacterial stimuli and may account for the local activation of all types of reactional episodes in leprosy." (PMID 17927586, 2007). "Using CD1a+ LC-like DCs derived from leprosy patients, two CD1a-restricted αβTCR-expressing T cell clones, B2.1 and B2.11, were generated." (PMID 40709176, 2025). "CD1a pattern and intensity of immunostaining of dermal dendritic cells throughout the spectrum of leprosy." (PMID 37223172, 2023). "The highest number (11%-20%) of epidermal DCs stained by CD1a was observed in two cases of TT and one case of BT leprosy." (PMID 37223172, 2023). "The present study was conducted to assess the macrophage activation in the spectrum of leprosy using CD1a and Factor XIIIa immunohistochemical markers and to correlate the macrophage expression with the morphological spectrum and bacillary index." (PMID 37223172, 2023). "Marked accumulation of CD1a+ LC after mycobacterial stimuli was also described in leprosy skin lesions." (PMID 21603161, 2011). "In leprosy, for example, LC-like DCs and freshly isolated epidermal LCs present non-peptide antigens of Mycobacterium leprae to T cell clones derived from a leprosy patient in a CD1a-restricted and langerin-dependent manner." (PMID 36160158, 2022). "Langerhans cells in leprosy skin lesions express CD1a and langerin." (PMID 29643852, 2018). "The immunohistochemical approach using the antibody to CD1a may therefore be a useful tool in evaluating the immunological status of leprosy patients because of its ability to shed more light on the pathogenic mechanisms involved in RR and ENL." (PMID 17927586, 2007). "The number and distribution of CD1a+ skin cells and HLA-DR and intercellular adhesion molecule (ICAM)-1 expression were analysed in leprosy skin lesions and in delayed-type hypersensitivity (DTH) tests." (PMID 17927586, 2007).
acute lymphoblastic leukemia (5 papers, 2014 to 2024). Leukemia with an acute onset, characterized by the presence of lymphoblasts in the bone marrow and the peripheral blood. "Cultures of both AML and acute lymphoblastic leukemia blasts in vitro with various cytokine preparations have led to the expression of CD1a on the blast cells." (PMID 25343480, 2014).
Breast Tumours (5 papers, 1999 to 2017). "CD1a has been used widely to identify myeloid DCs, and often together with S100, to define DC populations in breast tumor tissues and TDLNs." (PMID 24088396, 2013). "CD1a+, CD1a+CD14+, and CD14+ DDC are subsets that range from more to less mature respectively; we found a clear shift to a predominance of immature CD14+ subsets among DC migrated from breast tumor-overlying skin." (PMID 23875023, 2013).
dendritic cell tumor (5 papers, 2010 to 2025). A dendritic cell tumor develops from the cells of the immune system. "However, indeterminate dendritic cell tumor, a rare type of dendritic cell tumor and originate from the alleged precursor cells of Langerhan cells, is indeed difficult to distinguish from Langerhans cell tumor because both tumors consistently express S-100 protein and CD1a." (PMID 23388086, 2013). "CD1a is a highly sensitive and specific marker of LCS, as compared to other dendritic cells and dendritic cell neoplasms." (PMID 26923635, 2013). "FDCS typically lacks expression of CD1a, desmin and CD45, which allows their differential diagnosis with interdigitating dendritic cell tumors, Langherhans cell tumors, histiocytic and lymphoid neoplasias." (PMID 20937101, 2010). "In general, the tumor cells of IDCS are positive for S-100 and Vim and negative for CD21, CD35 and CD1a, which are of benefit to differentiate IDCS from other dendritic cell neoplasms." (PMID 24396471, 2014).
inflammatory skin disease (5 papers, 2016 to 2024). Inflammatory skin disorders covers a broad category that includes many conditions ranging in severity, from mild itching to grave medical health complications These disorders are common in people of all ages and races. "Alteration of CD1a-dependent T-cell responses has recently been discovered to contribute to the pathogenesis of several inflammatory skin diseases." (PMID 38173286, 2024). "The colocalization of CD1a autoreactive T cells, CD1a proteins, and CD1a‐presented antigens within the skin suggests possible roles in inflammatory skin disease or homeostatic immunity of the skin." (PMID 26518614, 2016). "Under a chronically activated state, increases in certain proinflammatory cytokines could induce extra-cutaneous CD1a expression and further contribute to CD1a-dependent pathways of systemic inflammation and inflammatory skin disease co-morbidities." (PMID 36477177, 2022). "Anti-CD1a blockade was able to effectively inhibit recognition of GAS-infected K562-CD1a cells by IL-22-producing polyclonal ex vivo blood T cells, suggesting the possibility of therapeutic intervention in GAS-driven inflammatory skin disease." (PMID 37267382, 2023).
lung carcinoma (5 papers, 2016 to 2022). "Early studies examined langerin expression in bronchial biopsies of primary lung carcinomas from 12 patients and found infiltration of DCs within tumor tissues including LCs and CD1a+/langerin+ cells interspersed among tumor cells." (PMID 36160158, 2022). "Our study shows that lung cancer cells impair the differentiation of DCs, supported by decreasing CD1a up-regulation and the disappearance of CD14." (PMID 27050278, 2016). "Previously our study showed that lung cancer cells impair the differentiation and function of DCs, which is supported by changing phenotype (decreasing CD1a up-regulation and the appearance of CD14) and expression of high levels of IL-10." (PMID 27833081, 2016). "Therefore, the ratio of CD1a/CD14 is a critical indicator for assessing the differentiation degree of DCs in lung cancer." (PMID 27050278, 2016). "In addition to that CD1A expression might also be relevant in the context of immunotherapeutic approaches in lung cancer." (PMID 33953302, 2021). "Some, but not all, lung carcinomas produced GM-CSF and a good correlation exists between GM-CSF production and the number of CD1a+ LCs infiltrating these tumors." (PMID 36160158, 2022). "Therefore, IL-10 expression and CD1a/CD14 ratio are critical indicators for assessing the degrees of differentiation and function of DCs in lung cancer." (PMID 27833081, 2016).
T-cell acute lymphoblastic leukemia (5 papers, 2009 to 2024). Acute lymphoblastic leukemia of T-cell origin. "The phenotypic profiles of our patients are close to those reported in literature for B-lineage ALLs; for the T-cell ALL subgroup, the blast cells express more CD1a, surface CD3, and CD4 while expressing less TdT." (PMID 20041009, 2009). "T cell ALL is a unique separate ALL entity composed of different immunophenotypic and biologic subsets: thymic (CD1a +), mature (surface CD3 +), early (both negative) and its subcategory of early T cell precursor-ALL (ETP-ALL; myeloid markers positive, CD1a negative, CD8 negative, CD5 < 75%)." (PMID 36927623, 2023).